RPGRIP1L (RPGRIP1 like)
Diseases named in the same sentence as RPGRIP1L in open-access papers (continued):
Sharing a sentence is not in itself a finding about the gene and the disease.
kidney disease (3 papers, 2018 to 2023). "Patients with JS with renal disease (JS-R) exhibit the features of a kidney disorder that is predominantly juvenile nephronophthisis (NPH), without defects in the retina; mutations of NPHP1 and RPGRIP1L are associated with this phenotype." (PMID 30518138, 2018).
tumor (3 papers, 2016 to 2025). "Mechanistically, we found that RPGRIP1L promoted the activation of the Hedgehog signaling pathway, which in turn drived tumor proliferation and upregulated PD-L1 expression." (PMID 41469586, 2025). "Functional studies demonstrated that RPGRIP1L knockdown reduced genomic instability in tumor cells, as evidenced by decreased Phosphorylated Histone H2AX (γH2AX) expression, and suppressed tumor growth in mouse models." (PMID 41469586, 2025). "Mechanistically, RPGRIP1L is thought to suppress tumor cell transformation in part by regulating MAD2, a mitotic checkpoint protein whose inactivation is realized by the proteasome." (PMID 27293550, 2016).
cancer (2 papers, 2021). A tumor composed of atypical neoplastic, often pleomorphic cells that invade other tissues. "The results verified six mutations in three genes, OBSCN, TTN, and RPGRIP1L, in at least one cancer type." (PMID 33597970, 2021). "Interestingly, its interactor RPGRIP1L, which encodes for RPGRIP1 Like, is localized in ciliated cells and seems to regulate the activity of the ciliary proteosome, which was observed to be altered in many cancers." (PMID 34715892, 2021).
metabolic disorders (1 paper, 2024). "Those chronic disorders were related to metabolic disorders and congenital anomalies coded by AGTX, GALC, GRHPR, RDH12, and RPGRIP1L." (PMID 38553482, 2024).
RPGRIP1L also shares sentences with these, for which no sentence is quoted: Leber congenital amaurosis (4 papers); Retinal dystrophy (3); Ataxia (2); cone-rod dystrophy (2); Hepatic fibrosis (2); retinal disease (2); Alport syndrome (1); Anophthalmia (1); autism (1); Bardet-Biedl syndrome (1); Bardet-Biedl syndrome type 13 (1); cerebellar ataxia (1); cerebello-oculo-renal syndrome (1); COACH syndrome 3 (1); cystic kidney disease (1); cystic kidneys (1); Genetic diseases (1); Griscelli syndrome (1); homocysteinemia (1); idiopathic scoliosis (1); Insulin resistance (1); kidney damage (1); liver disease (1); Lowe syndrome (1); Meckel syndrome, type 5 (1); Methylmalonic aciduria (1); microphthalmia (1); myopia (1); neurological disorders (1); ocular motor apraxia (1).
A further 11 diseases each share a sentence with RPGRIP1L in 1 paper.